TINF2 (TERF1 interacting nuclear factor 2)
Diseases named in the same sentence as TINF2 in open-access papers (continued):
Sharing a sentence is not in itself a finding about the gene and the disease.
neuroblastoma (1 paper, 2022). Neuroblastoma (NB) is the most common solid, extracranial childhood tumor. "A rare TINF2 frameshift mutation (c.591delG) encoding a truncated mutant TIN2 protein (p.W198fs) was identified in a 6-years-and-3-month-old Chinese girl with neuroblastoma (NB) by next generation sequencing and confirmed by Sanger sequencing." (PMID 35873475, 2022).
non-Hodgkin lymphoma of the lung (1 paper, 2024). "There was only 1 individual with TINF2 who had not undergone transplant with a malignant neoplasm; they had a non-Hodgkin lymphoma of the lung." (PMID 39661387, 2024).
Pancytopenia (1 paper, 2025). An abnormal reduction in numbers of all blood cell types (red blood cells, white blood cells, and platelets). "Mutant mice hosting a Tinf2 allele reflecting a dyskeratosis congenital disease mutation (i.e., the Tinf2 DC allele) exhibit homozygous lethality, with heteroxygous TIN2DC/+ individuals displaying decreased fertility, shortened telomeres, and pancytopenia." (PMID 40141057, 2025).
renal carcinoma (1 paper, 2024). A carcinoma arising from the epithelium of the renal parenchyma or the renal pelvis. "Shelterin expression predicted patient survival in 24 cancer types, with TERF1, TERF2, TINF2, and POT1 significantly expressed in testicular, AML, prostate, breast and renal cancers, respectively, and TPP1 in AML and skin cancer." (PMID 39578854, 2024).
testicular cancer (1 paper, 2024). A primary or metastatic malignant neoplasm that affects the testis. "Except for TINF2 in lung and testicular cancers and TPP1 in uterine cancers, shelterin proteins correlate positively across all 40 cancer types analyzed." (PMID 39578854, 2024).
tumor syndrome (1 paper, 2020). "The data establish that the TINF2 truncations predispose to a tumor syndrome." (PMID 33258446, 2020).
urinary bladder cancer (1 paper, 2024). A primary or metastatic malignant neoplasm involving the bladder. "Of 17 individuals with TINF2, 3 (17.6%) had malignant neoplasms after transplant (2 HNSCC and 1 urinary bladder cancer)." (PMID 39661387, 2024).
cancer (24 papers, 2009 to 2025). A tumor composed of atypical neoplastic, often pleomorphic cells that invade other tissues. "Specific truncating mutations of TINF2 that encodes an integral member of the shelterin complex, critical for telomere protection, have previously been reported to cause a high risk for cancer." (PMID 35590014, 2023). "Cancer is more common in people with TBDs; around 1%–4% of patients with TINF2 mutations have cancer, which tends to affect tissues with rapid turnover (skin, mucus membranes, and bone marrow)." (PMID 35873475, 2022). "To date, only a few clinical studies have specifically evaluated the association between cancer risk and specific germline mutations in patients with DC/TBDs and showed that about 1%–4% patients had an underlying TINF2 mutation." (PMID 35873475, 2022). "Inactivation of one TINF2 allele through truncation mutations results in inherited cancer predisposition with high penetrance and severity." (PMID 33258446, 2020). "Our data and the co-segregation of the TINF2 p.W198fs variant with cancer in one large family, argues that this is not the case." (PMID 33258446, 2020). "Here, we describe cancer-prone families with two unique TINF2 mutations that truncate TIN2, a shelterin subunit that controls telomere length." (PMID 33258446, 2020). "Based on these reports, TINF2 acts as a haploinsufficient tumor suppressor also outside the DC context, and specific truncation mutations resulting in long germline telomeres cause inherited cancer predisposition with high penetrance and severity." (PMID 35590014, 2023). "Nevetheless, the exact incidence of cancers in patients with TINF2 mutations is unclear." (PMID 35873475, 2022). "Moreover, as a haploinsufficient tumor suppressor gene, mutations in TINF2 and other shelterin genes have been linked to increased cancer risk." (PMID 35873475, 2022). "Here, we describe heterozygous loss-of-function mutations in TINF2 in cancer-prone families." (PMID 33258446, 2020). "Based on these families, we suggest that carriers of the reported TINF2 variants might benefit from regular thyroid and dermatological surveillance as well as more general cancer surveillance." (PMID 33258446, 2020). "In the TINF2 cases affected by inherited cancer predisposition, it is extremely unlikely that genome instability contributes to tumorigenesis since we have not detected loss of telomere protection or genome instability in heterozygous cell lines whose genotype mimic the patient status." (PMID 33258446, 2020). "We imagine that the TINF2 mutations exert their cancer-promoting effects in the first weeks or months after fertilization, resulting not only in long telomeres in the germline but also in all other stem cell compartments that are relevant to cancer development later in life." (PMID 33258446, 2020). "Paradoxically, cancer cells (CCs) require adequate shelterin to sustain their rapid proliferation, and increased levels of shelterin proteins such as TERF1, TERF2, and TINF2 are associated with tumour development." (PMID 39578854, 2024). "Changes in several shelterin components, such as TERF2, TERF1, and TINF2, have been identified in human cancers, highlighting potential therapeutic targets to combat cellular ageing and telomerase activity in various cancers." (PMID 39578854, 2024). "Recently, increasing evidence suggests that telomere maintenance genes, such as TERT, TERC, TERF1, TERF2, TINF2, TERF2IP and POT1 are associated with cancer risk." (PMID 22970196, 2012). "This comprehensive examination of the transcriptional regulation of the TINF2 gene will shed important light on the role(s) this gene plays in the pathogenesis of human hematological diseases and cancer." (PMID 21731707, 2011). "Current results indicate that not all TINF2 truncating variants are high cancer risk alleles and add further evidence that different TINF2 mutations can have very diverse effects on the disease phenotype." (PMID 35590014, 2023).
cancer (continued). "Patients who developed cancer from the DC/TBD NCI cohort presented different patterns of inheritance: 48.1% had AD-nonTINF2 disease, 29.6% had AR/XLR disease, 3.7% had TINF2-associated disease, and 18.7% had an unknown mode of inheritance." (PMID 36091172, 2022). "However, some data associate DKC1, TERC, TERT, TINF2, and WRAP53 genes with a higher risk of cancer." (PMID 36091172, 2022). "The cancer-causing TINF2 mutations that create long germline telomeres without affecting telomere protection now remove the ambiguity." (PMID 33258446, 2020). "Symbols with vertical lines denote individuals who have developed cancer but have not been tested for TINF2 mutations." (PMID 33258446, 2020). "Thereby TINF2 p.Tyr312Ter does not seem to result in either elongated or shortened telomeres, the cellular level features associated with TINF2 mutations related to inherited high-risk cancer predisposition and DC, respectively." (PMID 35590014, 2023). "Thus, TINF2 is not haploinsufficient for telomere protection and the TINF2 mutations are unlikely to induce cancer-promoting genome rearrangements." (PMID 33258446, 2020). "However, the temporal increase in TERT and TINF2 gene expression and enzyme activity may be linked with growth advantage and increased tumour progression in DFT, as it is in human cancers." (PMID 22952882, 2012). "Furthermore, both TERT and TINF2 have been suggested as potential therapeutic targets in human cancer and increasing our understanding of the role of these genes in Devil Facial Tumour Disease may open novel avenues for disease treatment." (PMID 22952882, 2012). "High expression of TINF2, a negative regulator of telomerase activity, in DFT cells suggests that telomere elongation is highly regulated in this cancer." (PMID 22952882, 2012). "TERT and TINF2 RNA levels did not associate with TCN, a finding also observed in other human cancer cell lines." (PMID 22952882, 2012).
tumor (12 papers, 2012 to 2023). "We did not, however, observe any significant association between TCN and TERT or TINF2 expression in the tumour samples (Spearman rank correlation, R = −0.31, P = 0.36, N = 11; R = −0.05, P = 0.88, N = 11, respectively)." (PMID 22952882, 2012). "According to this reasoning, TINF2 would be a tumor suppressor gene with a very specific window of opportunity, exerting its effect early in development but not later." (PMID 33258446, 2020). "We conclude that TINF2 acts as a haploinsufficient tumor suppressor that limits telomere length to ensure a timely Hayflick limit." (PMID 33258446, 2020). "In the tumours, the expression level of TINF2 was significantly lower than that of TERT (Two-sided Mann-Whitney U-test; U = 27, P = 0.03, median TINF2 = 0.51, median TERT = 3.58)." (PMID 22952882, 2012). "TERT and TINF2 expression showed substantial variation across tumour samples." (PMID 22952882, 2012). "In addition, the shelterin‐complex genes: TINF2 and POT1 exhibited a twofold increased number of expression outliers among clinically aggressive tumours." (PMID 35979662, 2022). "As proxies for telomerase activity in tumour tissue samples we investigated the expression of the catalytic subunit of telomerase (TERT) and one of the main components of shelterin, the TRF1-intercating nuclear factor 2 (TINF2)." (PMID 22952882, 2012). "The higher expression of both TERT and TINF2 may also protect DFT cells from genomic instability and enhance tumour proliferation." (PMID 22952882, 2012).
infection (9 papers, 2014 to 2024). The state of being infected such as from the introduction of a foreign agent such as serum, vaccine, antigenic substance or organism. "TINF2-mutated fibroblasts were transduced with the GeCKO lentiviral CRISPR knockout library at a low multiplicity of infection (MOI) to prevent transduction of cells with multiple viruses/gRNAs." (PMID 37717172, 2023).
retinopathy (2 papers, 2016 to 2020). "These include patients with DKC and potentially mutations other than TINF2, in whom retinopathy may occur occasionally." (PMID 33097095, 2020). "Although further work will be required, it is tempting to speculate that TINF2 mutations may mount a more robust DDR, distinct from other DC mutations, that could alter the underlying DC pathology as evidenced by the presence of retinopathy in this particular patient." (PMID 26859482, 2016). "Hence, even if calcifications may be seen in other entities, including CRMCC, HS, and DKC, this feature in combination with retinopathy, early onset of BMF, and the molecular evaluation of TINF2 is a valuable predictor of RS." (PMID 33097095, 2020).
hematologic malignant neoplasms (1 paper, 2024). "The cumulative incidence of hematologic malignant neoplasms leveled off at 2% by age 30 years in individuals with AR/XLR and 19% by age 70 years in individuals with AD–non-TINF2." (PMID 39661387, 2024).
TINF2 also shares sentences with these, for which no sentence is quoted: colorectal cancer (3 papers); gastric cancer (3); aplastic anemia (2); breast tumor (2); Hoyeraal-Hreidarsson syndrome (2); idiopathic pulmonary fibrosis (2); interstitial lung disease (2); lung disease (2); acute promyelocytic leukemia (1); anaemia (1); Astrocytoma (1); Ataxia - pancytopenia (1); bleeding (1); brain tumour (1); cervical cancer (1); chronic lymphocytic leukemia (1); chronic myelomonocytic leukemia (1); Cirrhosis (1); colon carcinoma (1); cryptogenic cirrhosis (1); Dubowitz syndrome (1); emphysema (1); Fanconi anemia (1); genetic diseases (1); GI dysfunction (1); glioblastoma (1); hemorrhage (1); Hyperglycemia (1); Infertility (1); lung carcinoma (1).
A further 17 diseases each share a sentence with TINF2 in 1 paper.